CD151 (CD151 molecule (Raph blood group))
Diseases named in the same sentence as CD151 in open-access papers (continued):
Sharing a sentence is not in itself a finding about the gene and the disease.
breast cancer (continued). "Based on the association of α6β4 integrin in mammary tumourigenesis, the relevance of CD151 in breast cancer was also hypothesised." (PMID 22294188, 2012). "In addition, CD151 ablation was found to inhibit the migration, invasion, and spreading of breast cancer cells in relation with its effect on the subcellular distribution of integrins, suggesting the promoting role of CD151 in breast tumour progression." (PMID 22294188, 2012). "Furthermore, a recent study has shown that the depletion of CD151 attenuates pulmonary metastasis of breast cancer cells by regulating transforming growth factor β signalling." (PMID 22294188, 2012). "Furthermore, in the same study, CD151 overexpression was shown to correlate with decreased survival of patients with breast cancer when assessed in 56 cases." (PMID 22294188, 2012). "CD151 expression may be a potential molecular therapeutic target for breast cancer, especially in the Luminal A and QNBC subtypes, and advanced stages of cancers." (PMID 22294188, 2012). "The delayed breast cancer progression by CD151 ablation was also shown in mouse xenograft models established using basal-like cell line, suggesting that CD151 may be a novel therapeutic target in certain breast cancer subtypes." (PMID 22294188, 2012). "GDF11, CD151, PAFAH1B2 and YTHDF2 may play a pivotal role in the predisposition of metastasis to the bone from breast cancer, whilst DPP9, FAS, ZNF519, RPP14 and FAU may be actively involved in the adaptative colonisation of metastatic breast cancer cells in bone." (PMID 35685372, 2022). "Overall, these findings suggest that CD151 dependency is associated with the ZEB1+/ERα+ status and that CD151 could be a promising target for inhibiting cell proliferation, migration, and invasion during partial EMT induced by ZEB1 in ERα+ breast cancer." (PMID 35440541, 2022). "This may also represent another layer of complexity of CD151 action in human ER+ breast cancer." (PMID 33919420, 2021). "Consistently, previous studies had showed that CD151 ablation can sensitize multiple tumor cell types to gefitinib by increasing cells apoptosis and disruption of CD151 can sensitize breast cancer cells to ErbB2 inhibitors, this findings also confirmed our hypothesis." (PMID 34108040, 2021). "Also unexpectedly, the CD9/CD81 complex, but not CD151, was required to promote α3β1 association with PKCα in breast carcinoma cells, and a PKC inhibitor mimicked aspects of the CD9/CD81-silenced cell motility defect." (PMID 23613949, 2013). "Thus, correlative analyses with CD151 and key proteins of these cascade pathways may be interesting to investigate so that the pathogenic role of CD151 in HER2-positive breast cancer is further clarified." (PMID 22294188, 2012). "Compared with these two previous studies of CD151 in breast cancer, our study utilised a larger number of cases that had sufficient follow-up data, including subtype analysis and thus this might be a reason for the discrepancy in results between this study and previous studies." (PMID 22294188, 2012). "It's the first time the PM proteomics of OS was studied and CD151 antigen was found to be over-expressed in cell lines and confirmed its overproduction in OS clinical tissue, which was also observed to be up-regulated in breast cancer but down-regulated in colorectal cancer." (PMID 20470422, 2010). "Specifically, CD151 has been identified as a part of MET and integrin complexes, such as β4 or α3/α6 integrins, in gastric carcinoma and salivary glands, and breast cancer cells." (PMID 39769452, 2024). "We used the GOBO database and extracted the data for ERα+ breast cancer patients in relation to ZEB1 and CD151 expression levels." (PMID 35440541, 2022). "In order to address this question, we studied the effect of Cd151 deletion on de novo breast tumorigenesis and spontaneous metastasis in the very well characterized MMTV/PyMT transgenic breast cancer mouse model." (PMID 25012362, 2014).
breast cancer (continued). "These chromosomes contain genes that are commonly involved in the invasion, metastasis and pathogenesis of breast cancer, including c-MYC on 8q24; HRAS, CD151, CTSD on 11p15; CCND1 on 11q13; and TOP2A on 17q21." (PMID 24456987, 2014). "Since the mammary tumors of MMTV/PyMT mice primarily metastasize to the lungs, we examined the lungs of Cd151+/+ and Cd151−/− PyMT mice at the time of dissection, which corresponds to 6 to 7 weeks after tumor onset." (PMID 25012362, 2014). "Since CD151 is positively correlated with TGFβ, we treated MCF10A normal breast cancer cells with TGFβ to investigate the involvement of miR-506 in the regulation of EMT." (PMID 23717581, 2013). "We wondered whether CD151 might be a therapeutic target during hybrid EMT stages when ZEB1 and ERα are simultaneously expressed in breast cancer cells." (PMID 35440541, 2022). "It was shown that absence of CD151 in breast cancer cells affected the compartmentalization of TGFβ receptor 1 thereby disturbing TGF-β1-induced activation of p38, which correlated with reduced lung adhesion and decreased metastases." (PMID 29946318, 2018). "The detailed clinical significance of CD151 overexpression in a large cohort of patients with breast cancer has not been previously reported." (PMID 22294188, 2012). "In this study of 886 breast cancer cases, we found that CD151 overexpression is an independent negative predictor of OS in patients with breast cancer and its worse impact on OS was retained in Luminal A and QBNC subtypes." (PMID 22294188, 2012). "CD151 has previously been postulated to play important roles in a number of cancers including colorectal and breast cancers but no studies had previously identified or examined its expression and function in ovarian cancer." (PMID 22272937, 2012). "CD151 overexpression may be a potential molecular therapeutic target for breast cancer, especially in QNBC subtype and more advanced stages of breast cancer." (PMID 22294188, 2012). "When CD151 overexpression was compared among the breast cancer subtypes (Luminal A, Luminal B, HER2, BLBC, and QNBC), CD151 overexpression varied significantly according to the breast cancer subtype (P<0.001)." (PMID 22294188, 2012). "Moreover, a systematic approach examining the incidence of CD151 expression and the significance of CD151 on clinical outcomes in breast cancer subtypes has not been undertaken." (PMID 22294188, 2012). "However, CD151 overexpression was found to be an independent negative prognosis factor for OS but not for DFS of patients with breast cancer in this study." (PMID 22294188, 2012). "The immunophenotyping of different breast cancer cell lines revealed that all cells displayed high expression levels of CD147 and CD151, irrespective of the subtype, which was also confirmed by confocal imaging." (PMID 36834918, 2023). "Overall, these data indicate that the ability of the CD9/CD81 complex to promote α3β1 integrin-dependent motility is not restricted to the MDA-MB-231 breast cancer model, although, unlike MDA-MB-231 cells, A431 cells also exhibit an ongoing requirement for CD151 for rapid migration on LM-332." (PMID 23613949, 2013).
hepatocellular carcinoma (26 papers, 2011 to 2025). A malignant tumor that arises from hepatocytes. "Nevertheless, research pertaining to the involvement of CD151 in hepatocellular carcinoma (HCC) neovascularization and its association with migrasomes remains inadequate." (PMID 38840183, 2024). "In summary, our study explores the complex relationship between CD151 and migrasome production, and the impact of migrasomes on angiogenesis in Hepatocellular Carcinoma (HCC) progression." (PMID 38840183, 2024). "Our research highlights CD151 as a marker for these bodies, notably upregulated in hepatocellular carcinoma (HCC) compared to normal liver tissue." (PMID 38840183, 2024). "This study further found that SNHG3 overexpression induced EMT in hepatoma cells through miR‐128/CD151 cascade activation." (PMID 36420693, 2023). "The clinical data also suggested an unrecognized association between high SNHG3 and tumor metastasis, which was consistent with Zhang’s conclusion in hepatocellular carcinoma wherein SNHG3 induced EMT processing via modulating the miR-128/CD151 signaling." (PMID 31534128, 2019). "LncRNA SNHG3 also was characterized to be involved in the microRNA pathway in hepatocellular carcinoma, wherein the modulation of miR-128/CD151 signaling by SNHG3 induced epithelial-mesenchymal transition (EMT) and sorafenib resistance." (PMID 31534128, 2019). "In contrast, some miRNAs restrain cancer progression through targeting Tspans [for example, CD151 with miR-199a-3p and miR-124 in hepatocellular carcinoma, Tspan1 with miR-573 and miR-216a in pancreatic cancer, with miR-194-5p in cholangiocarcinoma, and with miR-573 in gastric cancer]." (PMID 38389703, 2024). "Tumor growth potential, neoangiogenesis and metastasis following injection with a hepatocellular carcinoma cell line was also inhibited in mice that were treated with mAb 9B, which was shown to specifically disrupt the interaction between CD151 with integrin α6β1." (PMID 32117989, 2020). "CD151 is upregulated in chronic liver disease and hepatocellular cancer." (PMID 28473332, 2017). "For instance, in hepatocellular carcinoma (HCC), TSPAN9 appears to be more prominently associated with migrasome activity, whereas in colorectal cancer (CRC), CD151 emerges as a central player." (PMID 40299331, 2025). "In hepatocellular carcinoma (HCC), mortalin was found to stabilize CD151-dependent tetraspanin-enriched microdomains and contribute to the progression of HCC." (PMID 36819105, 2023). "We show that CD151 is upregulated in chronic liver disease and hepatocellular carcinoma (HCC) and is regulated on endothelium by tissue remodeling and procarcinogenic factors." (PMID 28473332, 2017). "Our previous studies revealed that tetraspanin CD151 plays multiple roles in the progression of hepatocellular carcinoma (HCC) by forming a functional complex with integrin α6β1." (PMID 26756217, 2016). "Here we reveal a ceRNA interaction between PIK3C2A and CD151 mRNAs in hepatocellular carcinoma (HCC) cells." (PMID 27270320, 2016). "In this study, we mapped tetraspanin web proteins centered on CD151, in order to explore the role of CD151 complexes in the progression of hepatocellular carcinoma (HCC)." (PMID 21961047, 2011). "In the context of Hepatocellular Carcinoma (HCC), elevated CD151 levels correspond with increased migrasome marker (TSPAN4) levels, enhancing neovascular formation and promoting metastasis." (PMID 38840183, 2024). "In hepatocellular carcinoma (HCC), LAMC1 competes for miR-124 binding and acts as a trans-regulator to induce the expression of CD151." (PMID 35511773, 2022). "For example, in hepatocellular carcinoma (HCC), CD151 was overexpressed compared with normal liver tissues and the expression level was positively related to the metastatic potential of HCC cell lines." (PMID 34222025, 2021). "The reported substrates of ZDHHC2 also includes CD9 and CD151 in HEK293 cells, Lck in T cells, and CKAP4 in hepatocellular carcinoma and interstitial cystitis." (PMID 32587588, 2020).
hepatocellular carcinoma (continued). "In contrast, naïve and infected hepatoma cells showed comparable spread following stimulation with anti-CD9, anti-CD151 or -Beta-1 integrin." (PMID 24662676, 2014). "Expression of CD151 was found to correlate with expression of MMP9, and both correlated with poor prognosis in hepatocellular carcinoma." (PMID 22570691, 2012). "In the liver, CD151 is predominantly expressed in endothelial cells and supports lymphocyte adhesion mediated by the vascular cell adhesion protein 1 (VCAM-1 or CD106) in inflammation and hepatocellular carcinoma." (PMID 36012131, 2022). "Similarly, SNHG3 repressed the degradation of CD151 by competing with miR-128, contributing to the epithelial–mesenchymal transition (EMT) and sorafenib resistance in hepatocellular carcinoma." (PMID 33817254, 2020). "TM4SF5 expression is positively correlated with tumorigenic CD151 expression, but is negatively correlated with tumor-suppressive CD63 expression in mouse fibrotic and human hepatic carcinoma tissues, indicating cooperative roles of the tetraspanins in liver malignancies." (PMID 25033048, 2014). "We propose that CD151 regulates the activity of VCAM-1 during lymphocyte recruitment to the human liver and could be a novel anti-inflammatory target in chronic liver disease and hepatocellular cancer prevention." (PMID 28473332, 2017). "To ascertain whether ligation of other cell surface proteins induce hepatoma spread we evaluated antibodies specific for other tetraspanin family proteins (CD9 and CD151) and the non-tetraspanin cell surface expressed protein scavenger receptor B1 (SR-B1)." (PMID 24662676, 2014).
lung carcinoma (19 papers, 2019 to 2025). "The tetraspanin, Cluster of Differentiation 151 (CD151), is ubiquitously expressed in adult tissue, especially in the lungs where it has been implicated in lung cancer, asthma, influenza, and idiopathic pulmonary fibrosis (IPF)." (PMID 32117989, 2020). "Given the strong association between CD151 and lung cancer, especially adenocarcinoma which is the most common NSCLC subtype, CD151 expression has proven to be especially informative on patient prognosis." (PMID 32117989, 2020). "Furthermore, CD151 was shown to be associated with increased disease severity and poorer survival outcome in asthma and lung cancer, respectively." (PMID 32117989, 2020). "In patients with unclear tissue subtypes of lung cancer, the AUC of detection of CD151 was 0.68, CD171, 0.61, and TSPAN8, 0.60." (PMID 34094979, 2021). "Nonetheless, the clinical significance of CD151 expression shows that CD151 has great potential to be developed as a diagnostic biomarker which may be helpful for early detection or screening, or as a prognostic biomarker given its relevance in predicting lung cancer or asthma severity." (PMID 32117989, 2020). "In lung cancer cells, CD151 knockdown resulted in impairment of several cancer-promoting processes including cell survival, migration, invasion, and matrix adhesion." (PMID 32117989, 2020). "In various cancer cell lines (A431, MDA-MB-231, and A549 lung carcinoma) treated with gefitinib, we observed an increase in total CD151 protein levels in a dose- and time-dependent manner." (PMID 30778617, 2019). "This highlights the potential of CD151 as a target for lung cancer treatment." (PMID 38982031, 2024). "We found that patients with high CD151 levels had a higher rate of disease‐specific death from lung cancer than those with low CD151 levels (p = 0.045), supporting our conclusion that CD151 overexpression is of prognostic value for lung cancer patients without EGFR mutations." (PMID 38982031, 2024). "We then divided the patients into four subgroups based on their CD151 levels and whether they had mutations in the EGFR gene, which is often altered in lung cancer." (PMID 38982031, 2024). "This study investigates CD151, a protein linked to cancer progression, in non‐small cell lung cancer (NSCLC) patients without epidermal growth factor receptor (EGFR) mutations." (PMID 38982031, 2024). "Notably, overexpression of several of these genes, such as CD151 and CD44, has been observed in lung cancer and is associated with poor prognosis." (PMID 34663427, 2021). "Indeed, integrins have been reported to control the EGFR signaling pathway and induce EGFR clustering, so we believe that CD151 regulates EGFR signaling pathway by controlling integrins in lung cancer." (PMID 34108040, 2021). "It remains to be observed whether the same hypoxic conditions can reduce CD151 in a lung cancer setting." (PMID 32117989, 2020). "The Extracellular Vesicle Array (EV Array) to phenotype lung cancer-related proteins in plasma exosomes may be a simple, minimal invasive tool, by which exosomal proteins CD151, CD171 and tetraspanin 8 are found to be higher in lung cancer patients of all histological subtypes." (PMID 33504342, 2021). "CD151, CD171, and tetraspanin 8 represent very reliable markers for lung cancer characterization and identification." (PMID 38893088, 2024). "Eventually, a total of four genes including, CD151, MMP1, PVT1, and SKP2 genes were selected as reference genes based on their known functions in lung cancer progression and lymph node metastasis which have been pointed out in the found articles." (PMID 37185598, 2023). "Three membrane proteins, CD151, CD171 and TSPAN8, on the sEVs derived from lung cancer tissues can be used to distinguish different pathological types of lung cancer." (PMID 34094979, 2021). "They further showed that gefitinib upregulated CD151 protein levels in MDA-MB-231 breast and A549 lung carcinoma cell lines, respectively." (PMID 32117989, 2020).
lung carcinoma (continued). "High CD151 expression levels in non‐small cell lung cancer (NSCLC) patients lacking epidermal growth factor receptor (EGFR) mutations are associated with poorer clinical outcomes." (PMID 38982031, 2024). "Exosome protein profiling comparing a cohort of lung cancer patients with non-cancer patients revealed that CD151 was one of the markers found to be upregulated in lung cancer." (PMID 32117989, 2020). "Additionally, CD151, CD171, and tetraspanin 8 were important markers to distinguish patients with all histology lung cancer from cancer-free individuals thus highlighting promising use of exosomes in lung cancer diagnosis." (PMID 39464709, 2024). "Moreover, the capabilityof the MagLev platform to distinguish non-cancerous exosomes fromcancerous ones by targeting CD151 as a biomarker for lung cancer wasdemonstrated." (PMID 38520356, 2024). "Exosomal CD151 could be a biomarker for distinguishing lung cancer patients with every subtype from noncancer patients." (PMID 35158999, 2022). "For instance, research conducted by Sandfeld-Paulsen identified proteins such as CD151 and CD171 as viable biomarkers capable of distinguishing between lung cancer and non-lung cancer patients." (PMID 39194595, 2024). "They found that CD151, CD171 and tetraspanin 8 were the most effective biomarkers for distinguishing between those with and without lung cancer, as well as differentiating between various types of lung cancer histology." (PMID 37641132, 2023). "CD151, CD171, and TSPAN8 were concluded to be promising exosomal biomarkers for distinguishing patients with lung cancer from patients without cancer." (PMID 35158999, 2022). "The exosomal markers CD151, CD171, and tetraspanin 8 were identified as the strongest differentiators of patients with lung cancer of all histological subtypes from patients without lung cancer." (PMID 34281588, 2021).